ZNF585B (zinc finger protein 585B)
Description:
May be involved in transcriptional regulation.
Synonyms: FLJ14928; SZFP41; Zfp27
Tractability: PROTAC: ubiquitination databases record sites on it.
Gene: Protein-coding gene on chromosome 19 (37,181,579 to 37,218,153, reverse strand). Ensembl gene ENSG00000245680.
Subcellular location: Nucleus
Subcellular location (Human Protein Atlas): Cytoplasmic bodies; Nucleoplasm
Pathways (Reactome):
Gene expression (Transcription): Generic Transcription Pathway
Gene Ontology:
Molecular function: transcription cis-regulatory region binding
Biological process: regulation of transcription by RNA polymerase II; developmental process; regulation of DNA-templated transcription
Cellular component: nucleus
Genetic constraint (gnomAD): Loss-of-function variants: 7 observed, 15.23 expected, observed/expected ratio (o/e) 0.46, 90% interval 0.26 to 0.86. The upper end of that interval is the gene's LOEUF score, 0.86, which puts it in group 3 of 6, group 1 being the genes least tolerant of losing a copy. Missense variants: 747 observed, 945.75 expected, observed/expected ratio (o/e) 0.79, 90% interval 0.74 to 0.84. Synonymous variants: 290 observed, 323.22 expected, observed/expected ratio (o/e) 0.9, 90% interval 0.81 to 0.99.
Homologues: Orthologues: chimpanzee ZNF585B (98% identical). Paralogues in human: ZNF585A (95% identical), ZNF484 (53% identical), ZNF41 (49% identical), ZNF658 (44% identical), ZNF197 (43% identical), ZNF33B (42% identical), ZNF175 (40% identical), ZNF605 (39% identical), ZNF470 (39% identical), ZNF546 (39% identical), ZNF841 (38% identical), ZFP28 (38% identical), and 164 more.
Diseases named in the same sentence as ZNF585B in open-access papers:
ZNF585B is named in the same sentence as 2 diseases in open-access papers, as found by Europe PMC text mining. Sharing a sentence is not in itself a finding about the gene and the disease. The quoted sentences say what the papers report.
oropharyngeal cancer (1 paper, 2015). Carcinoma, predominantly squamous cell, arising from the epithelial cells of the oropharynx. "All but ZNF14 are located on the 19q13 locus, which was shown to be epigenetically silenced in oropharyngeal cancer, supporting the hypothesis that ZNF160, ZNF420, ZNF585B, and ZNF71 are epigenetically regulated in a coordinated fashion." (PMID 26544568, 2015).
tumor (1 paper, 2015). "Of all remaining five ZNF protein genes, ZNF14, ZNF160, ZNF71, ZNF420 and ZNF585B, DNA methylation was significantly higher in tumor samples, as compared to normal controls." (PMID 26544568, 2015).